TIMP3 (TIMP metallopeptidase inhibitor 3)
Diseases named in the same sentence as TIMP3 in open-access papers (continued):
Sharing a sentence is not in itself a finding about the gene and the disease.
ovarian carcinoma (19 papers, 2012 to 2025). A malignant neoplasm originating from the surface ovarian epithelium. "Survival analysis of the TCGA ovarian cancer cohort revealed that higher expression levels of TIMP3, BRAF, and ITGB1 were significantly associated with poorer overall survival." (PMID 41294900, 2025). "TIMP3 has been identified as an ovarian cancer-specific biomarker of cancer-associated fibroblasts (CAFs) associated with cancer progression, chemoresistance, and poor prognosis by integrating several bioinformatic approaches." (PMID 38542164, 2024). "In the group of ovarian cancer patients subjected to neoadjuvant chemotherapy Kaplan-Meier curves demonstrated that high baseline TIMP3 levels were associated with total patient survival time longer by 12.4 months." (PMID 29304854, 2018). "In another study, a higher ADAMTS-1, ADAMTS-5, aggrecan, versican and TIMP-3 expression in malignant ovarian tumors compared to benign tumors was associated with a shorter overall survival in ovarian cancer patients." (PMID 29393911, 2018). "Moreover, TIMP3 was associated with ovarian cancer prognosis, positively correlated with tumor resistance, and negatively correlated with immunotherapy response." (PMID 40357367, 2025). "We also observed a positive correlation between TIMP3 and fibroblast-presented expression in the ovarian cancer study." (PMID 40357367, 2025). "The results showed that the expression of TIMP3 was correlated with the resistance of ovarian cancer cells to the drug I-BET151." (PMID 40357367, 2025). "Collectively, this study defines a core regulatory axis—miR-192-5p/ITGB1/TIMP3/BRAF—that underpins differences in ovarian cancer progression and patient survival." (PMID 41294900, 2025). "Secondly, the risk of ovarian cancer increased with age in association with MMP3, MMP10, MMP7, TIMP3, POX/PRODH, PYCR1, PYCR3 to indicate degenerative histological changes." (PMID 38397798, 2024). "Higher TIMP3 levels are inversely correlated with ascites in patients with advanced stages of ovarian cancer." (PMID 38542164, 2024). "Second, signatures increased in collagen expression together with LOX, THBS2, TIMP3 and SPARC have also been associated with decreased survival in ovarian cancer." (PMID 33379263, 2020). "Comparison of mean TIMP3 levels demonstrated significantly lower concentrations of the marker in the group of patients with ovarian cancer compared to patients with benign cysts (138 pmol/L; 285 pmol/L), respectively)." (PMID 29304854, 2018). "TIMP3 median levels were negatively correlated with ascites in ovarian cancer patients qualified for neoadjuvant chemotherapy (r = 0.682, p = 0.02) and for primary surgery (r = 0.711." (PMID 29304854, 2018). "Aim of this research was to assess MMP3 and TIMP3 as prognostic factors among patients with ovarian cancer." (PMID 29304854, 2018). "Median TIMP3 levels revealed significantly lower concentrations in a group of patients with ovarian cancer compared to patients with endometrial cysts, p = 0.001." (PMID 29304854, 2018). "Finally, TIMP3 was found to mediate drug resistance in ovarian cancer in the drug resistance database, and TIMP3 predicted ovarian cancer efficacy to immunotherapy." (PMID 40357367, 2025). "We further analyzed the effect of TIMP3 expression in ovarian cancer on patient survival." (PMID 40357367, 2025). "There is evidence that TIMP3 participates in tumor invasion as well as preferential methylation in ovarian cancer, while a similar study showed that TIMP3 mRNA expression was higher in ovarian cancer patients than healthy individuals." (PMID 37124501, 2023). "TIMP3 had a diverse expression level among 45 human ovarian cancer cell lines, which might be due to their different characteristics." (PMID 36424614, 2022). "The serum levels of MMP-3 and TIMP-3 correlate with survival in ovarian cancer." (PMID 35629249, 2022).
ovarian carcinoma (continued). "The gene–pathway enrichment heatmap and DepMap analyses collectively emphasize ITGB1, TIMP3, and BRAF as central molecular hubs in ovarian cancer biology." (PMID 41294900, 2025). "In metastatic ovarian cancer, fibroblasts induce macrophage polarization through the TIMP3-regulated CXCL signaling pathway, which affects the prognosis of ovarian cancer patients and drug resistance of ovarian cancer cells." (PMID 40357367, 2025). "We also found that apoptosis-related genes, URI1, PAK2, PARP1, CLU and TIMP3, were highly expressed, while immune-related genes, UBB, RPL11, CAV1, NUPR1 and Hsp90ab1, were lowly expressed in ovarian cancer cells." (PMID 37124501, 2023). "RT-qPCR analysis revealed that URI1, PAK2, PARP1, CLU, and TIMP3 were significantly upregulated, while UBB, RPL11, CAV1, NUPR1, and Hsp90ab1 were significantly downregulated in the ovarian cancer samples." (PMID 37124501, 2023). "The expression distribution of 6-OMAGs mRNA in 45 human ovarian cancer cell lines obtained from the CCLE dataset demonstrated that there were large variations in the expression levels of FBN1, TIMP3, and UCHL1 between cell lines." (PMID 36424614, 2022). "Moreover, only the expressions of MMP7, MMP12, TIMP3, CAT and Nrf2 were affected by the clinical stage of ovarian cancer." (PMID 38397798, 2024). "However, it is not clear why there was a parallel increase in TIMP-3 expression, the tissue inhibitor of ADAMTS-1 and ADAMTS-5, in malignant ovarian neoplasms compared to benign epithelial ovarian neoplasm." (PMID 29393911, 2018).
cervical carcinoma (17 papers, 2014 to 2026). A carcinoma arising from either the exocervical squamous epithelium or the endocervical glandular epithelium. "Compared with CC, patients with cervical cancer carrying genotypes CT/TT in TIMP-3 rs9862 had a higher risk of developing moderate and poor cell grading (grade 2/3, OR: 3.61, 95% CI: 1.14-12.01, p=0.012)." (PMID 35813301, 2022). "In relating the TIMP-3 genetic variants rs9619311, rs9862 and rs11547635 to the clinicopathological parameters, only women with CT/TT in rs9862 were found to display a higher risk of developing cervical cancer with moderate and poor cell differentiation." (PMID 35813301, 2022). "Therefore, we devised this study to explore the significance of TIMP-3 genetic polymorphisms in the development and progression of cervical cancer." (PMID 35813301, 2022). "In previous reports, we observed that TIMP3 showed high expression in pancreatic cancer tissues, and TIMP3 was upregulated in cervical cancer cell lines and cervical squamous cell carcinoma tissues." (PMID 40357367, 2025). "An inverse correlation between miR-21 and TIMP3 expression has been demonstrated in cervical cancer samples." (PMID 38542164, 2024). "TIMP3 promoter methylation is often found in various cancers, including oral, gastric, and cervical cancer." (PMID 38542164, 2024). "Compared to patients with lower expression levels of TIMP3 in cervical cancer tissues, those with higher TIMP3 expression correlate with a lower survival rate; however, no significance has been observed." (PMID 38542164, 2024). "A study with contrasting findings has indicated that TIMP3 is upregulated in cervical cancer cell lines (HPV-related QG-U cells and HPV-negative Yumoto cells) and cervical SCC tissues." (PMID 38542164, 2024). "miR-G-10 represses TIMP3 expression, preventing the increased migration and invasiveness of cervical cancer cells." (PMID 38542164, 2024). "miR-221/222 have been demonstrated to target the 3′ untranslated regions (UTR) of TIMP3 in cervical cancer and lead to an increase in the levels of MMP2 and MMP9, as well as the promotion of cell migration and invasion in cervical cancer." (PMID 38542164, 2024). "For example, TIMP3 was downregulated in cervical cancer and was related to poor prognosis in cervical cancer patients, and miR-21-5p target binding to TIMP3 modulated the development of cervical cancer." (PMID 36591507, 2022). "Although this study is the only research investigating the relationships between TIMP-3 SNPs and cervical cancer, there are several limitations present." (PMID 35813301, 2022). "TIMP3 is involved in restricting invasion and migration of cells and is usually methylated in cervical cancer." (PMID 31766427, 2019). "TIMP3 was similarly moderately methylated in both cervical cancers and normal cervical tissues and was therefore excluded from the biomarker panel." (PMID 25826459, 2015). "Until now, no study investigates the involvement of TIMP-3 genetic polymorphisms in the development of cervical cancer." (PMID 35813301, 2022). "To date, no study investigates the implications of TIMP-3 genetic polymorphisms in the occurrence of cervical cancer and patient prognosis in Taiwanese women." (PMID 35813301, 2022). "After sorting the data, we selected MEG3, TIMP3, DAPK1, and SOX1 as being the most hypermethylated genes specific for the incipient stages of cervical carcinoma, while MLH1 and MALAT1 were chosen as the most hypomethylated genes." (PMID 35682732, 2022). "Moreover, a decreased expression of TIMP-3 has been reported in cervical intraepithelial neoplasia and cervical cancer related to HPV, which in turn may be responsible implicitly by an impaired extracellular matrix degradation activity and cyto-architectural abnormalities." (PMID 36713871, 2022). "Hypermethylation was however less frequent in cervical cancer in most genes, particularly in CDH13 (P < 0.001) and TIMP3 (P = 0.025)." (PMID 25065733, 2014).
cervical carcinoma (continued). "Furthermore, the strong immunoreactivity of TIMP3 has been detected in both nuclear and cytoplasmic patterns in HSIL and invasive cervical cancer tissues." (PMID 38542164, 2024). "The proportion of methylated TIMP3 in cervical cancer is significantly higher than that in normal cervical tissue." (PMID 38542164, 2024). "Other genes reportedly hypermethylated in cervical cancer with little to no methylation in normal or low-grade CINs include DAPK1, RARB, TIMP3, CCNA and FHIT." (PMID 25826459, 2015).
diabetes (16 papers, 2013 to 2024). "TIMP-3 expression was markedly reduced in monocytes from individuals with increased risk of diabetes and atherosclerosis." (PMID 35207132, 2022). "TIMP3 is the most highly expressed TIMP in the kidney and has a broad protease inhibition profile, and we and others have already demonstrated that loss of TIMP3 contributes to the onset and progression of DN in mouse models of diabetes and in human patients." (PMID 33634991, 2021). "Interestingly, pericyte TIMP-3 is known to be reduced in diabetic nephropathy and retinopathy and this appears to contribute to capillary loss and renal fibrosis in diabetes." (PMID 39544367, 2024). "In addition, TIMP-3 expression inversely correlates with the susceptibility of mice to develop diabetes and vascular inflammation." (PMID 35207132, 2022). "Secondly, Timp3 was genetically ablated in the Akita mouse, which carries an autosomal dominant allele consisting of a missense mutation in the Ins2 gene and recapitulates aspects of human diabetes." (PMID 35207132, 2022). "Interestingly, preserved renal TIMP3 expression in diabetic MacT3 mice was associated with protection against diabetes‐induced kidney damage and albuminuria." (PMID 33634991, 2021). "Loss of TIMP3, an Extracellular matrix-bound protein, is a hallmark of diabetic nephropathy in human and mouse models, suggesting its pivotal role in renal diseases associated to diabetes." (PMID 34181080, 2021). "Next, we treated MacT3 mice with the pancreatic islet cell toxin STZ in order to test the protective effect of the overexpression of TIMP3, directly in the kidney, during the progression of diabetes." (PMID 34181080, 2021). "We and others have demonstrated that loss of TIMP3 contributes to the onset and progression of diabetic kidney disease (DKD) in mouse models of diabetes." (PMID 34181080, 2021). "In diabetic mice the targeting of TIMP3 system improved kidney structure and function, representing a valid approach to develop new avenues to treat this severe complication of diabetes." (PMID 33634991, 2021). "It is reported that TIMP3 expression is reduced in mice with diabetes, and TIMP3 silencing contributes to DN development." (PMID 34446088, 2021). "Eight‐week‐old rats were operated femoral fracture or sham, following the injection of streptozotocin (STZ) to induce diabetes one week later in fractured rats, and then, new generated tissues were collected for measuring the expression of miR‐222 and TIMP‐3." (PMID 31691506, 2020). "We monitored the blood glucose level, serum insulin, miR222 expression and TIMP‐3 expression, respectively, after the induction of diabetes from day 4 to day 42 during the bone healing." (PMID 31691506, 2020). "These proteins we considered to be diabetes-typical, including two members of the complement system, C4 and C9, ApoE, fibrillin, fibronectin, TIMP-3 and Prolargin/PRELP, a proteoglycan." (PMID 29284024, 2017). "There is only one endogen inhibitor of ADAM-17, known as tissue inhibitor of metalloproteinase 3 (TIMP3), which activity is reduced in obesity, atherosclerosis, diabetes and insulin resistance." (PMID 26578976, 2015). "After grouping patients based on their diabetes status, we found that genetically higher levels of TIMP3 had a significant impact on eGFRcrea in participants without diabetes (OR:1.003,95%CI (1.001-1.006),P IVW:0.007), but not in participants with diabetes (PIVW = 0.057)." (PMID 38774282, 2024). "Three of these coding genes (BCL2, HIF1A, and TIMP3) were common genes in diabetes and DR." (PMID 34707685, 2021). "Among the top modulated adipokines were inflammatory mediators (C-reactive protein, endocan, EN-RAGE), extracellular matrix regulating factors (Serpin A8, TIMP-1, TIMP-3), and resistin, an adipokine proposed to be an important link between obesity and diabetes." (PMID 30524378, 2018). "Other diabetes-specific proteins were ApoE, Timp3, fibrillin, fibronectin, and PRELP." (PMID 29284024, 2017).
diabetes (continued). "Next, we treated WT and Timp3−/− mice with STZ for 12 weeks to generate overt diabetes." (PMID 23401241, 2013). "Actually, Stat1 was over-expressed in Timp3−/− diabetic kidney compared to the WT; moreover, abolishing Stat1 expression by RNA interference caused a complete rescue of FoxO1 expression, suggesting a possible role of STAT1 in linking Timp3 deficiency to FoxO1 regulation." (PMID 23401241, 2013). "Our study demonstrates a previously unknown mechanism in which the absence of TIMP3, a metalloprotease inhibitor, exacerbates renal damage in response to a chronic hyperglycaemic stress caused by diabetes." (PMID 23401241, 2013). "Pharmacological inhibition of ADAM17 led to an amelioration of the pathology, thus indicating that TIMP-3 links the interplay between reduced insulin action and aberrant ADAM17 activity in diabetes and vascular inflammation." (PMID 35207132, 2022). "Interestingly, TACE activity is controlled by TIMP3, an endogenous inhibitor of TACE, and thus, TIMP3/TACE modulation is commonly observed in insulin resistance, diabetes, inflammation, and tumor angiogenesis." (PMID 38558505, 2024). "Diabetes induced an increase in ADAM17 activity in the diabetic state, and ADAM17 activity was significantly higher in Timp3−/− mice compared to WT diabetic littermates; we also found that ADAM17 activity was increased at the same extent in both right and left kidneys of the two strains." (PMID 23401241, 2013). "In light of this, the purpose of our work was to use a two-sample MR technique to examine the relationship between TIMP3, CKD and renal function (measured by biochemical markers and the presence or absence of diabetes)." (PMID 38774282, 2024).